WWTR1 (WW domain containing transcription regulator 1)
Diseases named in the same sentence as WWTR1 in open-access papers (continued):
Sharing a sentence is not in itself a finding about the gene and the disease.
angiosarcoma (4 papers, 2020 to 2024). A malignant tumor arising from the endothelial cells of the blood vessels. "Examples include case 60, a malignant neoplasm with a vascular immunophenotype in which an angiosarcoma was favoured on histological grounds, but was found to have a WWTR1::CAMTA1 fusion allowing a diagnosis of epithelioid haemangioendothelioma to be made." (PMID 38997407, 2024). "Therefore, a genetic evaluation was requested for clarification, revealing a negative result for the WW domain-containing transcription regulator protein 1 - calmodulin binding transcription activator 1 (WWTR1-CAMTA1) fusion gene, validating the diagnosis of an angiosarcoma." (PMID 39734979, 2024).
cervical cancer (4 papers, 2015 to 2024). A primary or metastatic malignant neoplasm involving the cervix. "Finally, we investigated the clinical relevance of WWTR1 expression in cervical cancer patients using the TCGA cohort." (PMID 38987584, 2024). "WWTR1 was amplified in around 13% of cervical cancer patients." (PMID 38987584, 2024). "High WWTR1 expression correlated with reduced progression-free survival specifically in HPV18+ patients, when compared with non-HPV18+ cervical cancer patients (those harbouring other HR-HPV types or HPV-)." (PMID 38987584, 2024). "Further analysis revealed WWTR1 mRNA levels were increased in HPV18 +/HPV45+ but not HPV16+ cervical cancer cell lines." (PMID 38987584, 2024). "Copy number alteration driven dysregulated genes, such as PI3KCA, PI3KCB, DVL3, WWTR1, and ERBB2, are believed to play an important role in regulating immune cell infiltration, which might help to predict the prognosis of cervical cancer." (PMID 34925445, 2021).
colorectal cancer (4 papers, 2016 to 2021). A primary or metastatic malignant neoplasm that affects the colon or rectum. "Interestingly, in the subtype classification of colorectal cancers determined by Sadanandam and coworkers according to transcriptome analysis, WWTR1, Cyr61 and CTGF genes were associated with the stem cell-like signature and subtype." (PMID 27527859, 2016).
vascular sarcoma (4 papers, 2013 to 2025). A sarcoma arising from vascular tissue including arteries, veins, venous sinuses, arterioles and capillaries. "Furthermore, chromosomal translocations that generate fusion proteins containing TAZ (WWTR1-CAMAT1) or YAP (YAP-TFE3) are known disease-driving events in a vascular sarcoma called epithelioid hemangioendothelioma." (PMID 29642615, 2018).
head and neck squamous cell carcinoma (3 papers, 2019 to 2023). A squamous cell carcinoma that arises from any of the following anatomic sites: lip and oral cavity, nasal cavity, paranasal sinuses, pharynx, larynx, and salivary glands. "Expression of genes controlled by the Hippo downstream transcriptional coactivators YAP (Yes-associated protein 1) and TAZ (WWTR1, WW domain containing transcription regulator 1) is widely deregulated in human cancer including head and neck squamous cell carcinoma (HNSCC)." (PMID 31817001, 2019).
liver fibrosis (3 papers, 2023). "In addition, YAP and TAZ/WWTR1 have also been implicated in liver fibrosis." (PMID 36831330, 2023). "A gene cluster that was significantly downregulated in the Yap/Wwtr1 knockdown group contained genes primarily regulated by Tgfβ-1 and related to “hepatic fibrosis”, Stat3 pathway, and Th2 pathway— illustrating suppression of pro-fibrotic genes with depletion of Yap and Wwtr1." (PMID 36998974, 2023).
osteoporosis (3 papers, 2023 to 2024). A condition of reduced bone mass, with decreased cortical thickness and a decrease in the number and size of the trabeculae of cancellous bone (but normal chemical composition), resulting in increased fracture incidence. "Moreover, IFT20 and WWTR1 deficiency in osteoblasts exacerbated bone-fat imbalance in ovariectomy (OVX)- and high-fat-diet (HFD)-induced osteoporosis mouse models." (PMID 38562782, 2024). "By analysis of publicly available databases from bone samples of osteoporosis patients, we found that the expression of intraflagellar transport 20 (IFT20) and WW domain containing transcription regulator 1 (WWTR1) were significantly downregulated in osteoblast lineage cells." (PMID 38562782, 2024).
porocarcinomas (3 papers, 2023 to 2025). "Overall, YAP1 fusions were expressed in 92% of poromas and 7% of porocarcinomas, with 1 poroma associated with a WWTR1 fusion." (PMID 37627947, 2023). "Recent sequencing of these tumors demonstrated that 90% of poromas and ~70% of porocarcinomas exhibit YAP1 or WWTR1 gene fusions, with YAP1 fused to either MAML2 or NUTM1 and WWTR1 fused to NUTM1." (PMID 40491864, 2024). "Most poromas and porocarcinomas harbor YAP1::MAML2/NUTM1 or, rarely, WWTR1::NUTM1 fusions." (PMID 41350449, 2025).
squamous cell carcinoma (3 papers, 2020 to 2025). A carcinoma arising from squamous epithelial cells. "Although point mutations in core Hippo components are relatively rare, amplification of YAP1 and WWTR1 (TAZ) is more frequent in specific cancers, particularly squamous cell carcinoma and ovarian cancer." (PMID 41028521, 2025). "Intriguingly, mutually exclusive copy number gains of chromosome 3q and 11q22 (where YAP1 is mapped to) have been reported in squamous cell carcinoma and consistently, YAP1 and WWTR1 amplification were also found to be mutually exclusive in HNSCC." (PMID 32990596, 2020). "This was mainly attributed to the elevated proportion of cases with YAP1/WWTR1 genomic amplification and high expression heterogeneity of YAP/TAZ target gene signature, which correlated with decreased overall survival of patients with squamous cell cancers." (PMID 36551696, 2022).
endometriosis (2 papers, 2024 to 2025). The growth of functional endometrial tissue in anatomic sites outside the uterine body. "Interestingly, transcriptional analysis of uteri lacking Yap1 and Wwtr1 uncovered pathway annotations connected to endometriosis." (PMID 40378301, 2025).
epithelioid hemangioma (2 papers, 2015 to 2024). A hemangioma characterized by the presence of epithelioid endothelial cells. "Cases of epithelioid hemangioma and pseudomyogenic hemangioendothelioma have shown WWTR1::FOSB gene fusions." (PMID 40491864, 2024).
gastric cancer (2 papers, 2017 to 2019). A primary or metastatic malignant neoplasm involving the stomach. "Knockdown of WWTR1 in the gastric cancer AGS cells resulted in severe impairment in both the basal and the EGF-stimulated cell migration." (PMID 30976198, 2019). "It is interesting to examine the role of WWTR1 in cetuximab-resistant cell migration and invasion in these gastric cancer cell lines in our future studies." (PMID 30976198, 2019). "Our previous studies have initially identified the WWTR1 target gene product CYR61 as a prognosis biomarker and an associated factor of metastasis of GCA, and a driver protein for gastric cancer cell migration." (PMID 30976198, 2019). "Our studies have identified WWTR1 as a metastatic biomarker of GCA for poor prognosis, defined a role of WWTR1 in driving metastasis of gastric cancer, and suggested WWTR1 as a potential target for anti-metastatic therapy of GCA." (PMID 30976198, 2019). "In addition, the other downstream effector of the Hippo signaling YAP, similar to WWTR1, also promotes gastric cancer cell migration and metastasis." (PMID 30976198, 2019). "Furthermore, shRNA knockdown was used to determine the role of WWTR1 in promoting cell migration in gastric cancer cells." (PMID 30976198, 2019). "Furthermore, knockdown of WWTR1 markedly inhibits migration of gastric cancer AGS cells, suggesting a driving role of WWTR1 in metastasis." (PMID 30976198, 2019). "Taken together, the results from the IHC staining of GCA tumor tissues and the gastric cancer cell migration assay of the WWTR1-knockdown AGS cells suggest that WWTR1 is not only a clinical predictive index protein for poor prognosis of GCA but also a driver protein in metastasis of GCA." (PMID 30976198, 2019). "The WWTR1-activated cell migration signaling might mediate the cetuximab-resistance in these gastric cancer cell lines." (PMID 30976198, 2019). "Knockdown of WWTR1 by expression of the WWTR1 shRNA in gastric cancer AGS cells significantly inhibited cell migration, suggesting that WWTR1 might be a metastatic driver in GCA." (PMID 30976198, 2019). "Furthermore, knockdown of WWTR1 impaired migration of gastric cancer AGS cells." (PMID 30976198, 2019). "We used AGS, which is a highly metastatic gastric cancer cell line, to mimic GCA cells in determination of the effect of WWTR1 knockdown in cell proliferation and migration." (PMID 30976198, 2019). "Furthermore, we found that EGF stimulated AGS cell migration and knockdown of WWTR1 impairs both EGF-stimulated and EGF-independent AGS cell migration, suggesting that WWTR1 might mediate both EGFR-dependent and –independent gastric cancer cell migration." (PMID 30976198, 2019). "Currently, it is not clear whether the Hippo kinase cascade or the non-Hippo signaling pathway regulates the WWTR1 transcriptional activity in GCA or gastric cancer AGS cells." (PMID 30976198, 2019).
gastric cardia adenocarcinoma (2 papers, 2019 to 2020). A carcinoma that arises from glandular epithelial cells of the cardia of stomach. "Our studies have shown that WWTR1 is overexpressed in gastric cardia adenocarcinoma, expression of WWTR1 is reversely correlated with cumulative survival of GCA patients and significantly associated with GCA tumor invasion and metastasis." (PMID 30976198, 2019).
glioblastoma (2 papers, 2021 to 2025). The most malignant astrocytic tumor (WHO grade IV). "NRF2 regulates a key cholesterol-metabolizing bile acid-synthesizing enzyme (CYP7A1), in addition to the TAZ protein (encoded by the WWTR1 gene), in glioblastoma." (PMID 40507333, 2025).
hemangioendothelioma (2 papers, 2023 to 2024). A vascular proliferation characterized by the presence of prominent endothelial cells and the formation of vascular channels. "Moreover, variant WWTR1 and YAP1 gene fusions have been identified in cardiac EHE and subsets of retiform and composite hemangioendotheliomas, respectively." (PMID 40491864, 2024).
Insulin resistance (2 papers, 2023 to 2024). Increased resistance towards insulin, that is, diminished effectiveness of insulin in reducing blood glucose levels. "Placental DNA methylation of miR-548 and WWTR1 genes influence insulin sensitivity during pregnancy, and preterm birth and is linked to insulin resistance." (PMID 37434949, 2023).
ischemic stroke (2 papers, 2025). A stroke disorder caused by obstruction of blood flow to the brain, due to thrombotic (local blood clot formation) or embolic (due to a blood clot or other material traveling from another site) event. "Wwtr1 thus serves as a central mediator linking urea accumulation to astrocyte-driven neuroinflammation and neuronal injury following ischemic stroke." (PMID 41286951, 2025). "Building upon our proteomic findings, we sought to determine whether the Hippo pathway effector Wwtr1 mediates urea-induced neurotoxic polarization of astrocytes through regulation of the DNA damage response pathway under ischemic stroke pathological conditions." (PMID 41286951, 2025).
lung adenocarcinoma (2 papers, 2021). A carcinoma that arises from the lung and is characterized by the presence of malignant glandular epithelial cells. "Due to its susceptibility to ZIKV infection and rapid cytopathic effects, we chose A549, a human lung adenocarcinoma cell line, to validate the proviral phenotype of RhoV and WWTR1." (PMID 34834920, 2021).
myocardial infarction (2 papers, 2023). Gross necrosis of the myocardium, as a result of interruption of the blood supply to the area, as in coronary thrombosis. "Following myocardial infarction, depletion of Yap in myofibroblasts had minimal effect on heart function while depletion of Yap/Wwtr1 resulted in smaller scars, reduced interstitial fibrosis, and improved ejection fraction and fractional shortening." (PMID 36998974, 2023). "Yap/Wwtr1 depletion in myofibroblasts attenuates fibrosis and significantly improves cardiac outcomes after myocardial infarction and we identify Ccn3 as a factor downstream of Yap/Wwtr1 that contributes to adverse cardiac remodeling post MI." (PMID 36998974, 2023).
Obesity (2 papers, 2022 to 2025). Accumulation of substantial excess body fat. "Meanwhile, obesity increased messenger RNA (mRNA) level of Hippo pathway effectors Yap1, Wwtr1 (Taz), and their downstream targets, such as Ctgf and Cyr61." (PMID 36229481, 2022).
pancreatic cancer (2 papers, 2015 to 2023). "It should be noted that a successful targeting strategy conceivably require simultaneous disabling YAP and WWTR1, due to their functional redundancy and the commonly overlapping expression patterns in human pancreatic cancer." (PMID 26567630, 2015). "In esophageal, lung, and pancreatic cancer, as well as in GBM, WWTR1/TAZ has been shown to confer resistance to radiation." (PMID 38201456, 2023).
polycystic kidney (2 papers, 2009 to 2021). "Notably, adult fish with Wwtr1 overexpression developed phenotypes similar to those of human polycystic kidney disease (PKD)." (PMID 34545930, 2021). "A mouse knock-out of Wwtr1 displays a phenotype resembling human polycystic kidney disease, and the mouse knock-out of Shox2 is lethal with cleft palate, strongly suggesting that these genes are linked to human disease, although neither is annotated as a disease gene in OMIM." (PMID 19909546, 2009).
prostate carcinoma (2 papers, 2015 to 2021). A carcinoma that arises from epithelial cells of the prostate gland. "We noted that many Hippo pathway SNPs (one in MST1, three in STK3, two in LATS2, one in MOB1B, and six in WWTR1; total 13 out of 75) genotyped in our prostate cancer patient cohort were not in Hardy-Weinberg equilibrium (HWE)." (PMID 25707771, 2015).
pulmonary fibrosis (2 papers, 2023 to 2024). Chronic progressive interstitial lung disorder characterized by the replacement of the lung tissue by connective tissue, leading to progressive dyspnea, respiratory failure, or right heart failure. "Inactivation of Wwtr1 alone or in combination with Yap1 caused a drastic decrease in AT2 to AT1 cell differentiation, increased pulmonary fibrosis, and increased mortality in the latter (data not shown)." (PMID 37166104, 2023).
alcoholic cirrhosis (1 paper, 2024). "Further UMAP analysis indicated that the expression levels of genes such as PRDM16 and WWTR1 were elevated in alcoholic cirrhosis patients, while other genes like C18orf63 and RNU6ATAC39P showed decreased expression." (PMID 39588518, 2024).
astrocytomas (1 paper, 2025). "Indeed, analysis of the TCGA-GBMLGG dataset showed that both IDHmut-codeleted (oligodendrogliomas) and IDHmut-noncodeleted (astrocytomas) have higher WWTR1 and YAP1 DNA methylation, and lower WWTR1 and YAP1 gene expression, compared with IDHwt GBM." (PMID 41066183, 2025).
Barth syndrome (1 paper, 2022). Barth syndrome (BTHS) is an inborn error of phospholipid metabolism characterized by dilated cardiomyopathy (DCM), skeletal myopathy, neutropenia, growth delay and organic aciduria. "For example, in 2020, we were delighted to have the support of the Barth Syndrome Foundation when we proposed updating the symbol for the gene encoding the protein tafazzin from the confusing “TAZ” symbol (also commonly used in the literature for the unrelated WWTR1 gene) to simply “TAFAZZIN”." (PMID 35741066, 2022).
Blindness (1 paper, 2021). Blindness is the condition of lacking visual perception defined as a profound reduction in visual perception. "The Hippo pathway kinase cascade and its nuclear effectors Yes-Associated-Protein 1 (YAP1) and WW-domain-containing transcription regulator 1 (WWTR1, also known as TAZ) have been associated with ocular disorders that often lead to blindness in mice and humans." (PMID 34616723, 2021).
breast tumors (1 paper, 2016). "In addition, powerful stem cell regulators including YAP and c-MYC can mediate treatment-resistant epigenetic states, and WWTR1/TAZ has been shown to promote the CSC phenotype and EMT in breast tumors." (PMID 27608848, 2016).
cyst (1 paper, 2021). A sac-like closed membranous structure that may be empty or contain fluid or amorphous material. "Further studies revealed that loss of YAP1/WWTR1 reduced cyst formation in a Pkd1-deficient mouse model." (PMID 34545930, 2021). "Hematoxylin and Eosin (H&E) staining revealed that Wwtr1 OE larvae exhibited renal tubule dilation and glomerular cyst formation with enlarged Bowman's space, which were nearly identical to the phenotypes of stk3−/− mutants." (PMID 34545930, 2021). "Thus, overexpression of active Wwtr1 induced cyst formation in both pronephros and mesonephros of zebrafish." (PMID 34545930, 2021).
endometrial cancer (1 paper, 2022). Primary or metastatic malignant neoplasm involving the endometrium (mucous membrane that lines the endometrial cavity). "The Cancer Genome Atlas (TCGA)’s study of Endometrial cancer patients showed frequently amplified in YAP/TAZ, WWTR1, and STK3." (PMID 36552980, 2022).
fibrosis (1 paper, 2023). the formation of excess fibrous connective tissue in an organ or tissue in a reparative or reactive process. "While deletion of Yap alone did not result in observable changes in scar size or fibrosis, co-disruption of Yap/Wwtr1 resulted in significantly improved cardiac function as well as reduced scar size, interstitial fibrosis, and increased denatured collagen." (PMID 36998974, 2023).
head and neck cancer (1 paper, 2020). A primary or metastatic malignant neoplasm affecting the head and neck. "The functional loss of mutated FAT1 has also been reported to be associated with YAP1 activation in head and neck cancer, however, no enrichment of FAT1 mutation was seen among the YAP1-dependent nor WWTR1-dependent models in this study." (PMID 32990596, 2020).
Jaundice (1 paper, 2021). Yellow pigmentation of the skin due to bilirubin, which in turn is the result of increased bilirubin concentration in the bloodstream. "Unexpectedly, we observed that 40% (9 of 22 mice) of YAP-deficient mice developed jaundice within 6 to 8 weeks regardless of Atg7, Atg5, Pten, or Wwtr1 genotype." (PMID 34088666, 2021).
liposarcoma (1 paper, 2016). A usually painless malignant tumor that arises from adipose tissue. "Utilizing TCGA data, RNA levels of WWTR1 and YAP1 were demonstrated to be inversely correlated with overall survival in dedifferentiated liposarcoma and undifferentiated pleomorphic sarcomas." (PMID 27129148, 2016). "At an RNA level, expression of WWTR1 or YAP1 predicts overall survival in undifferentiated pleomorphic sarcoma and dedifferentiated liposarcoma." (PMID 27129148, 2016).
lung diseases (1 paper, 2024). "Ferroptosis has been implicated in various lung diseases, including COPD, highlighting the potential importance of WWTR1 in COPD pathogenesis." (PMID 38886662, 2024).
lung squamous cell carcinoma (1 paper, 2024). "Earlier studies have indicated that the amplification of YAP1 and WWTR1, which encode YAP and TAZ, respectively, has been observed in 16% of lung squamous cell carcinoma." (PMID 38499647, 2024).
lung tumor (1 paper, 2016). "Further experimentation with WWTR1/TAZ knockdowns resulted in decreased lung tumor progression, while constitutively active WWTR1/TAZ was found to be sufficient to drive lung tumor progression." (PMID 27602958, 2016).
medulloblastoma (1 paper, 2021). A malignant, invasive embryonal neoplasm arising from the cerebellum. "High expression of the transcriptional coactivator WWTR1 has been shown to be associated with a worse prognosis and affects cell proliferation in patients with medulloblastoma, regardless of subtype; however, phosphorylation of the S89 site leads to an inhibition of carcinogenesis and cell growth." (PMID 34569154, 2021).